E2F5 (E2F transcription factor 5)
Diseases named in the same sentence as E2F5 in open-access papers (continued):
Sharing a sentence is not in itself a finding about the gene and the disease.
tumor (57 papers, 2008 to 2026). "In LSCC, E2F5 may exacerbate tumor-associated inflammation and immune evasion by activating NETs-related signaling pathways (e.g., AMPK/Nrf2/HO-1)." (PMID 41488283, 2026). "Furthermore, elevated E2F1–3 and E2F5 expression levels were associated with a higher Gleason score (GS), advanced tumor stage, and metastasis." (PMID 35531101, 2022). "We demonstrate here that inhibition of retinoblastoma protein (RB) by the HPV‐E7 oncoprotein relieves E2F5, which then associates with Drp1 as a scaffolding protein, resulting in Drp1‐mediated mitochondrial fission, induction of ceramide‐dependent lethal mitophagy, and tumor suppression." (PMID 28606997, 2017). "The objective was to investigate the expression pattern of E2F transcription factor 5 (E2F5) in LSCC and its association with neutrophil extracellular traps (NETs), elucidating its role in the tumor microenvironment." (PMID 41488283, 2026). "In our study, we detected the expression of E2F5 and found that compared with adjacent normal tissues and NHA cells, the mRNA and protein expression levels of E2F5 were obviously upregulated in GBM tumor tissues and cell lines." (PMID 34784267, 2022). "As expected, the tumor volumes were apparently smaller in nude mice implanted with circCDK13- or E2F5-depleted PC3 cells than their corresponding control." (PMID 33390186, 2021). "The E2F5 expression of LGG showed a positive correlation with tumor purity and infiltrating levels of B cells, CD8+ T cells, and dendritic cells but not with infiltrating level of macrophages." (PMID 33381564, 2020). "More importantly, reintroduction of E2F5 into GBM cells reversed the tumor-suppressive function of miR-1179." (PMID 33381564, 2020). "The E2F5 expression was remarkably positively related to tumor purity (r = 0.34, P = 8.99e − 13) and neutrophils (r = 0.172, P = 3.99e − 04) in GBM." (PMID 33381564, 2020). "In this study, E2F5 expression was higher in OC tissues than in normal ones and was significantly and negatively correlated with tumor stage in patients with OC." (PMID 30967995, 2019). "In summary, our results indicated that the mRNA expression levels of E2F1, E2F3, E2F5, and E2F8 were significantly upregulated, and obvious and negatively associated with tumor stage for OC." (PMID 30967995, 2019). "In this report, we demonstrated that the expression of E2F5 in LC tissues was higher than that in normal tissues, but this expression was markedly correlated with tumor stage in patients with LC." (PMID 29754146, 2018). "Activation of Drp1 with E2F5‐mimetic peptide for inducing Drp1 mitochondrial localization enhanced ceramide‐mediated mitophagy and led to tumor suppression in HPV‐negative HNSCC‐derived xenograft tumors in response to cisplatin in SCID mice." (PMID 28606997, 2017). "Collectively, our findings indicate that FOXN3 functions as a tumor suppressor in HCC by downregulating the expression of E2F5." (PMID 27259277, 2016). "In the present work, we explore the expression profiles of FOXN3 in HCC and describe a biochemical and genetic interaction between FOXN3 and E2F5, which was originally identified based on its ability to act as a tumor suppressor in HCC." (PMID 27259277, 2016). "We have further characterized this regulatory signature by identifying increased E2f5, Erg1 and Csrnp1, molecules with anti-tumor properties, and Prdm1, whose gene product BLIMP-1 is a negative regulator of interferon (IFN) beta signaling." (PMID 26367386, 2015).
tumor (continued). "It is significant that a set of the most strongly associated proteins (p <0.01), DFFA, MAP2K1, E2F5, PARP1, predict for longer survival when decreased, which is as would be expected, as these proteins have tumour-promoting characteristics." (PMID 25177240, 2014). "For a better understanding of the molecular mechanism of miR-181a on tumorigenesis in vivo, the expression of Ki-67 and E2F5 were examined in tumor tissues by using immunohistochemical analysis." (PMID 24529171, 2014). "The retinoblastoma (Rb) gene family member p130 binds preferentially to the E2F5 transcription factor and forms a repressive E2F5/p130 complex that inhibits cell cycle progression and tumor growth." (PMID 18385796, 2008). "Given the demonstrated potential of E2F5 in regulating tumor proliferation and the microenvironment in other cancers, exploring its role in LSCC may provide novel insights into the molecular mechanisms underlying this disease." (PMID 41488283, 2026). "This suggests that E2F5 may drive tumor progression by regulating gene transcription and chromatin organization." (PMID 41488283, 2026). "E2F5 co-expressed genes were also involved in lymphocyte differentiation and negative regulation of leukocyte activation, suggesting that E2F5 may suppress anti-tumor immunity via SH2 domain binding." (PMID 41488283, 2026). "For instance, E2F5 may interact with the RNA Pol II complex to upregulate tumor-promoting genes or promote cell immortalization by regulating TRF1." (PMID 41488283, 2026). "As a transcription factor, E2F5 may participate in shaping the LSCC tumor microenvironment by directly or indirectly regulating the expression of NETs hallmark genes (e.g., S100A8/A9, LCN2), thereby influencing tumor progression." (PMID 41488283, 2026). "miR-154-5p acts as tumor suppressor in osteosarcoma and its upregulation inhibits the proliferation, migration and invasion in vitro as well as in-vivo tumor growth via the dysregulation in the pro-apoptotic proteins’ expression and the cell cycle regulators such as E2F5, Cyclin E1 and CDK2." (PMID 35755302, 2022). "Moreover, the mean tumor volumes and weight were significantly decreased by simultaneously silencing E2F5 and circCDK13 relative to each of them alone." (PMID 33390186, 2021). "Furthermore, immunohistochemical staining of Ki-67 to assess tumor cell proliferation revealed a reverse correlation between the miR-1-3p levels and the expression of E2F5 and PFTK1 protein and cell proliferation." (PMID 30185212, 2018). "Furthermore, patients with high E2F5 and/or PFTK1 expression are associated with a more aggressive tumor phenotype." (PMID 30185212, 2018). "E2F5 is cocited with ITGA5 in a paper about miRNA control of tumour cell invasion and metastasis." (PMID 25148247, 2014). "The key findings of the current study were that miR-181a could promote cell proliferation in vitro and tumor formation in vivo by targeting E2F5." (PMID 24529171, 2014). "It is likely that elevated E2F5 levels might be attributed to its increased production during cancer as a means by the body to arrest the proliferation of tumour cells during the early stage of the disease." (PMID 20181230, 2010). "Interestingly, E2F1, E2F3 and E2F5 were present on this supervised gene list and highly expressed in tumours with RB1 LOH." (PMID 18782450, 2008). "Additionally, the critical role of LCN2 in NETs suggests that E2F5 may further enhance NETs’ tumor-promoting effects by regulating LCN2." (PMID 41488283, 2026). "Furthermore, E2F5 gene belongs to E2F family of transcription factors, and it might play a role as a tumor suppressor gene and control the cell cycle process." (PMID 35360857, 2022).
tumor (continued). "Previous studies have indicated the role of miR-1-3p as a tumor suppressor in different cancers through different mechanisms, such as upregulating SFRP1, repressing E2F5 and PFTAIRE protein kinase 1, and modulating BDNF and TrkB." (PMID 38793064, 2024). "Analysis of TCGA-LIHC database showed that E2F4, E2F5, and E2F6 were upregulated in tumor tissues of HCC compared to normal tissues." (PMID 38166853, 2024). "This miRNA targets oncogenes and important genes for the initiation and progression of the tumor, including Myc, RAS, E2F1, E2F5, LIN28, ARID3B, PBX3, HMGA2 and long non-coding RNA H19." (PMID 36833380, 2023). "E2F transcription factor 5 (E2F5) has been discovered to be upregulated in GBM and is involved in regulating cell proliferation and tumor growth." (PMID 34784267, 2022). "circ_001569 was proved to sponge miR-145, finally increasing the expression level of miR-145 downstream target E2F5, Bag4, and FNL2 and promoting tumor proliferation and invasion." (PMID 35783017, 2022). "In this study, it was found that the expression level of E2F5 in human PAAD is significantly different from that of normal tissues, but the expression level has nothing to do with the tumor stage of PAAD patients." (PMID 33604289, 2020). "To date, several target mRNAs ascribed to miR-205 including PTEN and SHIP2, such as tumor suppressors, HER3, E2F1, E2F5, and PKCε, and oncogenes were identified." (PMID 31514456, 2019). "MiR-34a also behaves as a tumor suppressor in CRC by inhibiting cancer cell proliferation, invasiveness and metastasis through the down-regulation of formin like 2 (FMNL2) and E2F transcription factor 5 (E2F5) expressions." (PMID 30227605, 2018). "Several important cell cycle regulators were found differentially expressed in the reprogrammed tumours, including CDK4, E2F5, and CDKN1B (P27), WEE1, CDKN3." (PMID 29662623, 2018). "Mechanically, circ_001569 acts as a miRNA sponge to directly inhibit miR-145, and subsequently up-regulates miR-145 targets E2F5, BAG4 and FMNL2 to exert its tumor promoting function in CRC cells." (PMID 27058418, 2016). "The pRb homolog p130 is thought to be a tumor suppressor, and overexpression of p130 can inhibit cell proliferation by forming a strong repressive complex with E2F4 and E2F5." (PMID 18385796, 2008). "E2F5 showed significant high expression in LSCC epithelial cells and NETs-related cells, suggesting that it not only drives tumor cell proliferation but may also participate in LSCC progression by regulating microenvironment-related genes." (PMID 41488283, 2026). "In addition, miR-1-3p can significantly inhibit tumor volume in PCa bearing nude mice, and reduced expression of E2F5 and PFTK1 was detected in tumor tissue." (PMID 37907984, 2023). "In addition, IHC staining results revealed that the E2F5, Ki67, and MMP9 positive cells were markedly reduced in the tumor tissues of the sh-circFOXM1 group." (PMID 34784267, 2022). "We then investigated the relationships between the eight E2Fs and tumor immunology and found that E2F1, E2F3, E2F5, E2F6, and E2F7 expression was positively correlated with many immune cells, which might explain their favorable prognostic value." (PMID 34617871, 2021). "In addition, we detected the expression of E2F5, CDK13 and p21 in the xenograft tumor tissues by Western blot analysis." (PMID 33390186, 2021). "ETS transcription factor ERG (ERG), which is up-regulated in CRC tumours (however, its role in this tissue is not completely elucidated), and E2F transcription factor 5 (E2F5), which is involved in cell cycle control, are also targeted by miR-145-5p." (PMID 32610706, 2020). "Some studies demonstrated that miR-154-5p could act as a tumor suppressor gene through targeting CCND2, STAG2, E2F5, HMGA2 and TLR2." (PMID 30266084, 2018). "In addition, knockdown of E2F5 and PFTK1 mimicked the tumor-suppressive effects of miR-1-3p overexpression on PCa progression." (PMID 30185212, 2018).
tumor (continued). "Thus, circ_001569 acts as a miRNA sponge to directly combine with miR-145, and subsequently up-regulates miR-145 targets E2F5, BAG4 and FMNL2 to exert its tumor promoting function in CRC cells." (PMID 27058418, 2016). "The amplified genes with overexpression in each tumor sample groups might be the potential therapeutic targets for the specific tumor type, such as CCND1, CCNE2 for the ER group and E2F5, EIF2C2 for the PR group." (PMID 26273658, 2015). "Overall, these cells were rare and our analysis shows that E2f1 is able to largely rescue both the tumor and developmental phenotype, E2f3 is able to rescue the tumor phenotype but not the developmental phenotype and E2f5 can rescue neither." (PMID 25338120, 2014). "In summary, this study is the first to reveal E2F5’s high expression in LSCC and its potential interaction with NETs, demonstrating that E2F5 may promote tumor proliferation and microenvironment remodeling through transcriptional regulation, chromatin organization, and NAD+-related functions." (PMID 41488283, 2026). "According to the MiRTargetLink data, the expression level of some of the DREAM complex proteins, namely, E2F5, REL1 and REL2, are under the control of the miR-17-5p, miR-20a-5p and miR-93-5p, providing the proliferative potential and survival of the tumor cells." (PMID 36556382, 2022). "As a transcription regulator, FOXN3 has been reported to inhibit the expression of some tumour oncogenes, such as PIM2 and E2F5.9, 34 However, the negative correlation between FOXN3 and PIM2 or E2F5 was not validated in this study." (PMID 32078244, 2020). "The results showed that the expression levels of E2F2, E2F3, E2F6, and E2F8 are significantly correlated with the tumor stage of PAAD patients, while the expression levels of E2F1, E2F4, E2F5 and E2F7 are not correlated with the tumor stage of PAAD patients." (PMID 33604289, 2020).
cancer (37 papers, 2008 to 2026). A tumor composed of atypical neoplastic, often pleomorphic cells that invade other tissues. "Human E2F5 gene is oncogenic and overexpression of this gene was associated with worse clinical outcome in other cancers." (PMID 25329664, 2014). "Our data also indicated increased expressions of c-Myc, E2F4 and E2F5 genes, encoding transcription factors, which might be an attempt by cancer cells to stimulate their growth." (PMID 38674023, 2024). "In the realm of cancer molecular regulation, the transcription factor E2F5, a member of the E2F family, has increasingly garnered attention." (PMID 41488283, 2026). "E2F5 belongs to the E2F transcription factor family which is involved in cell growth, apoptosis, differentiation and cell cycle in cancers." (PMID 38271139, 2024). "Among them, we found a gene, E2F5, which had been shown to play a pro-oncogenic role in various cancers, so E2F5 was selected for our study." (PMID 34784267, 2022). "The expression levels of MYBL2, RBL1, LIN9, and E2F5 in various cancers were significantly upregulated." (PMID 35664326, 2022). "E2F5, a member of the E2F family, has been reported to be abnormally expressed in a variety of cancers." (PMID 34784267, 2022). "E2F5 acts as an important transcription factor that mainly regulates cell proliferation and migration in different human cancers." (PMID 34947956, 2021). "Aberrant expression of HDACs results in promoting the expression of E2F5, which mainly leads to increased cell proliferation and migration in different human cancers." (PMID 34947956, 2021). "Previous studies have demonstrated the oncogenic effect of E2F5 in different types of cancer, including HCC." (PMID 34348712, 2021). "Let-7c targets various oncogenes and cancer related genes such as IL6-R (interleukin-6 receptor) or E2F5 (E2F transcription factor 5)." (PMID 31658720, 2019). "Only 75% of early cancer cases showed higher levels of CA125 compared to 87.5% for E2F5 expression in early OEC cases." (PMID 20181230, 2010). "The E2F transcription factor 5 (E2F5) has an oncogenic function in a number of cancers, suggesting that E2f family transcription factors may be an essential downstream route." (PMID 38725047, 2024). "This is in accordance with the idea that miR-34a can regulate the cell-cycle regulator E2F5, which may be of great importance in comprehending the anti-cancer properties of miR-34a." (PMID 38725047, 2024). "Indeed, the regulation of E2F5 mRNA expression by some of these miRNAs has already been previously validated in other cancer types." (PMID 36896180, 2023). "Given the results of our immune infiltration analysis, we propose that E2F1, E2F2, E2F3, and E2F5 may potentially affect the progression of cancer through anticancer immunity." (PMID 35531101, 2022). "Basically, E2F5 links the cell cycle to post-transcriptional pathways, so it is essential for regulating cell growth, and also affects biological processes involved in cancer development." (PMID 36619866, 2022). "E2F5 may be involved in the development of other cancers, such as hepatocellular carcinoma, colon, breast, ovarian, osteogenic sarcoma, and esophageal squamous cell carcinoma." (PMID 36619866, 2022). "Likewise, similar trends were observed in E2F5 (benign vs cancer = 1.06 ± 0.04 vs. 1.64 ± 0.02; GS < 7: 1.46 ± 0.05, GS = 3 + 4: 1.52 ± 0.03, GS > 7: 1.81 ± 0.03)." (PMID 35531101, 2022). "In essence, E2F5 connects the cell cycle to the post-transcriptional mechanism and plays a crucial part in controlling cell growth and the transformation of biological processes that are incriminated in cancer development." (PMID 34947956, 2021). "E2F5 plays a significant role in the progression and development of human cancer." (PMID 34947956, 2021). "However, the E2F5 expression of GBM was positively related to cancer purity and neutrophil infiltration." (PMID 33381564, 2020).
cancer (continued). "Mechanistically, we showed that miR‐34c regulates Notch signaling and other cancer related pathways by targeting multiple genes (CCNE2, E2F2, E2F5, and HDAC1)." (PMID 35509638, 2022). "In accordance with the mRNA expression levels obtained from GEPIA, the protein expression of E2F1, E2F2, E2F3, E2F5, E2F7 and E2F8 were significantly higher in carcinoma tissues." (PMID 32117628, 2020). "The results showed that the mRNA levels of E2F1, E2F2, E2F3, E2F5, E2F7 and E2F8 were significantly lower in adjacent tissues compared with those in carcinoma tissues." (PMID 32117628, 2020). "Several of the predicted targets are known to be involved in cancer progression (E2F1, E2F5, ERBB, PTEN), invasion and metastasis (ZEB1/2, LRP-1)." (PMID 30510566, 2018). "Levels of HMGA1, HMGA2, PLAGL2, IGF2BP2, E2F5, and ARID3A transcripts were also inversely proportional to levels of Let-7 miRNA by examination of a cohort of 199 CRC patients from the TCGA Pan-Cancer analysis project." (PMID 26244988, 2015). "Even though the previous observation of E2F5 was altered in various cancer cells, the mechanisms have not been completely explained." (PMID 34947956, 2021). "In addition, some reported factors, including E2F5, PTEN/AKT/mTOR signaling, DUSP11, PRPF39, and LARP4, are involved in miR-513b-5p regulated cancer progression." (PMID 34120890, 2021). "E2F5 expression was found to be prominent in cancer samples (early and late malignant cases) and not in normal serum samples." (PMID 20181230, 2010). "Also, studies conducted using custom made microarray specific for OEC (Ovachip) showed upregulation of E2F5 in OEC, and it is found to play a key role in the neoplastic transformation of various cancer tissues as identified using microarray analysis." (PMID 20181230, 2010). "In approximately half of all epithelial ovarian borderline and malignant tumours, which included serous, mucinous, endometroid and other subtypes, E2F5 expression was demonstrable by IHC, compared with none of the normal and benign cases (z = 6.1; p < 0.001; n = 135)." (PMID 20181230, 2010). "If both were absent, it could be considered as non-cancer case with 93.75% NPV, while the presence of either CA125 or E2F5 is capable of detecting OEC in 97.92% of the actual cancer cases (sensitivity)." (PMID 20181230, 2010).